IFNG (interferon gamma)
Diseases named in the same sentence as IFNG in open-access papers (continued):
Sharing a sentence is not in itself a finding about the gene and the disease.
cervical squamous cell carcinoma (7 papers, 2017 to 2024). A squamous cell carcinoma arising from the cervical epithelium. "IFNG is an immune response gene and some of its single nucleotide polymorphisms (SNPs) are associated with cervical carcinogenesis and plays a decisive prognostic role in squamous cervical cancer." (PMID 36685937, 2022). "Our study revealed that the expression of IFNG is reversely correlated with the risk score, which suggested that IFNG could play a decisive prognostic role in squamous cervical cancer." (PMID 33160404, 2020). "We carried out a multivariate Cox regression analysis and developed six ARG-related prognostic signature for the survival prediction of patients with squamous cell cervical cancer (Risk score = − 0.63*ATG3–0.42*BCL2 + 0.85*CD46–0.38*IFNG+ 0.23*NAMPT+ 0.82*TM9SF1)." (PMID 33160404, 2020). "Next, we carried out multivariate Cox regression analysis and identified 6 genes (ATG3, BCL2, CD46, IFNG, NAMPT, TM9SF1) that were independently associated with OS in squamous cell cervical cancer patients." (PMID 33160404, 2020). "After univariate and multivariate Cox regression assay of differentially expressed ARGs, 6 ARG (ATG3, BCL2, CD46, IFNG, NAMPT, TM9SF1) related prognostic signatures for squamous cell cervical cancer were constructed." (PMID 33160404, 2020).
Chagas cardiomyopathy (7 papers, 2012 to 2025). A disease of the cardiac muscle developed subsequent to the initial protozoan infection by trypanosoma cruzi. "The finding that IFNγ is the most upregulated cytokine in the heart is in line with previous findings in murine infection and human Chagas cardiomyopathy studies." (PMID 29269773, 2017).
chronic gastritis (7 papers, 2009 to 2025). Inflammation of the stomach that is chronic in nature. "However, persistent IFNγ-driven inflammation also promotes tissue damage and chronic gastritis, underscoring its dual role in both protective immunity and disease pathology." (PMID 41573568, 2025).
Dengue hemorrhagic fever (7 papers, 2011 to 2023). A serious condition caused by Dengue virus infection. "THP-1 cells infected with dengue virus induced elevated levels of dengue hemorrhagic fever (DHF)-associated immunomediators such as interleukin (IL)-6, IL-8, interferon γ-induced protein-10 (IP-10), tumor necrosis factor alpha (TNFα) or IFNγ." (PMID 28788062, 2017).
disseminated candidiasis (7 papers, 2011 to 2022). Systemic candidiasis occurs when Candida yeast enters the bloodstream and may spread (becoming disseminated candidiasis) to other organs, including the central nervous system, kidneys, liver, bones, muscles, joints, spleen, or eyes. "While the protective role of IFNγ in disseminated candidiasis is evident, IL17-mediated protective response in this model has mostly been controversial." (PMID 33608410, 2021). "As a prototypic Th1 cytokine, interferon gamma (IFN-γ) has been used as adjunctive therapy for patients with both hematogenously disseminated candidiasis and multidrug-resistant OPC." (PMID 28325761, 2017). "Studies in IFNγ mutant mice have previously demonstrated a protective effect of this Th1 cytokine against disseminated candidiasis, suggesting that the elevated levels of this cytokine during infection may have a protective effect in C5-deficient AKR/J mice." (PMID 21533108, 2011).
fascioliasis (7 papers, 2012 to 2025). A parasitic infection that is caused by liver flukes, usually Fasciola hepatica, of sheep, goats, and cattle. "Moreover, the depletion of eosinophils during experimental fasciolosis was associated to a decreased production of IL-4, IL-5 and IFNγ, suggesting that in the absence of eosinophils the Th2 or Th1 immune responses are impaired." (PMID 33042162, 2020).
immunotoxicity (7 papers, 2013 to 2025). "Mechanistically, dual-dose Pam2ODN immunotherapy attenuated early interferon gamma-driven immunotoxicity, enhanced PRR and downstream signaling, induced essential antifungal effector cytokine pathways, and promoted recruitment, differentiation, and maturation of mononuclear phagocytes." (PMID 40197039, 2025).
lower respiratory tract infection (7 papers, 2010 to 2026). "SNPs in genes coding for interleukin (IL)-8, IL-19, IL-20, IL-13 mannose-binding lectin, interferon-gamma, and a regulated on activation, normal T cell expressed and secreted polymorphism have been associated with subsequent wheeze after RSV lower respiratory tract infection in term-born infants." (PMID 34386467, 2021).
lupus erythematosus (7 papers, 2015 to 2022). An autoimmune, connective tissue chronic inflammatory disorder affecting the skin, joints, kidneys, lungs, heart, and the peripheral blood cells. "Discoid lupus erythematosus (DLE) was significantly separated from control skin by all of the signatures (p < .05); IFNB1 had the greatest size (Hedge’s g = 12.4) followed by IFNW1 (g = 9.7), IFNG (g = 8.7), IFNA2 (g = 7.9), IL12 (g = 5.2), and TNF (g = 2.8)." (PMID 31044165, 2019).
mood disorder (7 papers, 2014 to 2023). A cognitive disorder a disturbance in which the person's mood is hypothesized to be the main underlying feature. "Recent studies indicate that an inflammatory component, involving several pro-inflammatory cytokines, such as interferon gamma and tumor necrosis factor alfa may be associated with mood disorders and that structural brain alterations may also play a role." (PMID 32719975, 2021). "Furthermore, proinflammatory cytokine expression and circulating levels, like interferon gamma (INFγ), TNFα, IL-6, and IL-1β, are associated with mood disorder symptoms." (PMID 32377159, 2020). "As the mood disorder pathology progresses, an increasing number of proinflammatory cytokines are observed, including elevated levels of interferon gamma (IFN-γ)." (PMID 24782789, 2014).
Multiple Organ Failure (7 papers, 2020 to 2024). A progressive condition usually characterized by combined failure of several organs such as the lungs, liver, kidney, along with some clotting mechanisms, usually postinjury or postoperative. "The presence of SNPs in the promoters of TNFA and IFNG genes also modulates their abnormal expression of TNF-α and IFN-γ, characterizing cytokine storms in response to pathogenic insults and ultimately leading to multiple organ failure." (PMID 39518964, 2024).
Neonatal sepsis (7 papers, 2011 to 2025). Systemic inflammatory response to infection in newborn babies. "IP-10 production in infants reflects a consequent Th1 response and as such, it may represent in conjunction with a reduced CD74 expression, despite IFNγ stimulation, a signature for severely dysregulated response associated with neonatal sepsis." (PMID 36509812, 2022). "First, we assessed the systemic pro-inflammatory response to neonatal sepsis, via quantification of circulating levels of key cytokines (TNF, IFNg, IL- 6, S100 A9, IL- 10, bFGF), chemokines (KC, RANTES, MCP- 1) and growth factors (G-CSF, GM-CSF)." (PMID 40307728, 2025). "M-CSF-MDMs, GM-CSF- and IFNγ-activated MDMs were exposed to GBS COH1, a reference strain for neonatal sepsis." (PMID 38035076, 2023).
nosocomial infection (7 papers, 2014 to 2026). An infection acquired in a hospital or other healthcare setting. "In addition, a recent study revealed that impaired IFNγ production of NK cells in is associated with nosocomial infection in critically ill patients following a systemic inflammatory response." (PMID 38426112, 2024). "A recent study reported decreased T-cell ex vivo PHA-induced production of IFNγ, IL-2 and IL-10 in children with septic shock that went on to develop persistent or nosocomial infection compared with septic shock children who did not." (PMID 27015534, 2016).
ocular infection (7 papers, 2005 to 2023). "A recent study using Ct elementary bodies (EBs) to stimulate PBMC from individuals exposed to ocular infection showed that cells with a classical NK cell phenotype (CD3-CD56+) were an additional major source of IFNγ." (PMID 23457650, 2013). "The resolution of Ct infection in animal models is IFNγ-dependent, involving Th1 cells, but whether this is the case in human ocular infection still needs to be confirmed." (PMID 23457650, 2013).
pemphigus (7 papers, 2015 to 2024). Pemphigus is a group of rare autoimmune diseases that cause blistering of the skin and mucous membranes (mouth, nose, throat, eyes, and genitals).This conditioncan occur at any age, but often strikes people in middle or older age. "Management with corticosteroids combined with TCM seemed to benefit pemphigus patients in terms of healing of lesions, prevention of complications and relapse, and reduced interferon-gamma (IFN-γ) level." (PMID 25793005, 2015). "One of the four studies compared the titer of specific antibodies for pemphigus between groups, as well as the levels of interleukin-10 (IL-10), interferon-gamma (IFN-γ), and soluble interleukin-2 receptor (slL-2R)." (PMID 25793005, 2015). "We validated significant upregulation of IFNG in DLE (p ~ 0.01), and a significant upregulation of CXCL8 and CSF3R in pemphigus." (PMID 39911479, 2024). "Specifically, we noted a unique expression of IFNG in DLE (p = 0.0213), a unique expression of TRAT1 and FOXO3A in EL patients (p < 0.0001 and p < 0.0001), and CXCL8 and CSF3R in pemphigus patients (p = 0.0002 and p = 0.0016)." (PMID 39911479, 2024). "Among the uniquely expressed genes in each disease, we observed significantly expressed IFNG in Discoid Lupus Erythematosus, TRAT1 in Epitheliotropic Lymphoma, and CXCL8 and CSF3R in pemphigus affected dogs." (PMID 39911479, 2024).
Pneumocystis infection (7 papers, 2011 to 2024). "Previous studies have shown that knockout of IFNγ in mice reverses PH caused by Pneumocystis infection, indicating the crucial role of this cytokine in the development of PH." (PMID 38548721, 2024). "Exogenous IFNγ significantly impaired FVB innate resistance, and rendered these normally resistant mice highly susceptible to Pneumocystis infection." (PMID 30283457, 2018).
pulmonary arterial hypertension (7 papers, 2017 to 2025). Pulmonary arterial hypertension (PAH) is a group of diseases characterized by mean pulmonary artery pressure >20 mmHg and elevated pulmonary arterial resistance leading to right heart failure. "The Nef constructs derived from HIV-pulmonary hypertensive donors demonstrated significant increases in Th1 cytokines IL-2, IL-12p70, and IFNg, as well as anti-inflammatory IL-10, but did not elicit innate immunity cytokines IL-1b or TNFa." (PMID 40559196, 2025).
T cell deficiency (7 papers, 2013 to 2025). "Although NOS2 expression is characteristically elicited by IFNγ-induced activation of STAT1-dependent gene transcription, expression of this cytokine was not affected by ChAT T-cell deficiency." (PMID 30973939, 2019).
tauopathy (7 papers, 2022 to 2025). Neurodegenerative disorders involving deposition of abnormal tau protein isoforms (tau proteins) in neurons and glial cells in the brain. "The pathological AstTau ASCs also displayed signatures of HALLMARK Apoptosis, Hypoxia, Complement, and the Interferon Gamma Response, adding to the growing body of knowledge that places import on the degenerative and inflammatory contributions of ASCs to the pathological development of tauopathies." (PMID 36271092, 2022). "Microglia may indeed act upstream of T-cell activation, since ablation of microglia prevented T-cell invasion and neurodegeneration in a mouse model of tauopathy which was dependent on IFNγ signaling." (PMID 38305941, 2024). "IFNγ secretion by immune cells could feed this interplay and exacerbate neurodegeneration in tauopathies." (PMID 37604929, 2023). "Inhibiting IFNγ signaling, or removing microglia by PLX3397 administration reduced p-Tau accumulation and brain atrophy in tauopathy mice." (PMID 37604929, 2023).
thyroid cancer (7 papers, 2016 to 2025). "The present study was specifically designed to test the possibility to inhibit the secretion of CXCL8 in thyroid cancer cells harboring specific genetic mutations and the characterization of the IFNγ signaling producing this inhibition appears by far behind the aim of our study." (PMID 27555670, 2016). "Research in thyroid cancer has revealed that Th1 lymphocytes can stimulate production of interferon-gamma (IFN-γ) and tumor necrosis factor-alpha (TNF-α), leading to release of CXCL10 and CXCL8." (PMID 40313970, 2025). "The TSH‐CAR‐T cells demonstrate effective antitumor activity against TSHR‐positive differentiated thyroid cancer (DTC) cell lines in vitro, accompanied by cytokine release (IFNγ, IL‐2) and robust proliferation." (PMID 40985353, 2025). "Aim of this study was to test the effect of IFNγ on the basal and TNFα-stimulated secretion of CXCL8 in TCP-1 and BCPAP thyroid cancer cell lines (harboring RET/PTC rearrangement and BRAF V600e mutation, resp)." (PMID 27555670, 2016). "Aim of the present study was thus to investigate whether IFNγ inhibits the basal and the TNF-α-stimulated secretion of CXCL8 in TCP-1 and BCPAP thyroid cancer cells." (PMID 27555670, 2016). "In conclusion, the results of the present study indicate that IFNγ, among its pleiotropic effects, is also able to inhibit CXCL8 secretion and cell migration in BRAF V600e mutated BCPAP but not in TPC-1 thyroid cancer cell line bearing the RET/PTC rearrangement." (PMID 27555670, 2016). "The present study demonstrates that IFNγ inhibits the basal and TNFα-stimulated secretion of CXCL8 in BCPAP, but not in TPC-1 thyroid cancer cell lines." (PMID 27555670, 2016). "Among IFNs, IFNγ was identified as the most powerful inhibitor; however, its ability to reduce the secretion of CXCL8 in thyroid cancer cells was not investigated previously." (PMID 27555670, 2016).
tuberculoid leprosy (7 papers, 2011 to 2024). A principal or polar form of leprosy in which the skin lesions are few and are sharply demarcated. "Some of the proteins analyzed in our study (ML1632, ML1685 and ML1556) induced strong and specific production of IFNγ in TT/BT and HHC groups, demonstrating their potential application for identification of those at risk of developing tuberculoid leprosy." (PMID 21269435, 2011). "These proportions could potentially skew the data in the favor of LL associations and weaken TT associations of traditional cytokines (IFNG with TH1 and tuberculoid leprosy)." (PMID 25412496, 2014).
acquired immunodeficiency (6 papers, 2013 to 2024). "We here present a severe case of acquired immunodeficiency with anti-IFNγ autoantibodies with simultaneous, disseminated infections with both viral and microbial pathogens." (PMID 33176707, 2020). "Encouraging evidence is emerging for the efficacy of rituximab, an anti-CD20- monoclonal antibody that leads to depletion of B lymphocytes, in IFNγ AAb-mediated acquired immunodeficiency." (PMID 31354706, 2019). "Reports of acquired immunodeficiency due to autoantibodies against interferon gamma in the adult population are increasing." (PMID 23336346, 2013). "Given the late presentation of symptoms - at the age of 49 years - and the absence of significant family or personal medical history, we suspected an acquired immunodeficiency due to the presence of anti-interferon-gamma autoantibodies." (PMID 23336346, 2013). "We previously reported antibodies against interferon-gamma (IFN-γ) in HIV− negative (HIV−) patients with acquired immunodeficiency presenting with repeated episodes of disseminated infection caused by uncommon opportunistic intracellular fungal, bacterial, and viral pathogens." (PMID 25329064, 2014).
Anosmia (6 papers, 2022 to 2025). An inability to perceive odors. "Anosmia/ageusia remain the main symptom associated with the more biomarkers with the more strength (IFNγ, IP-10, ICAM-1)." (PMID 40449327, 2025).
anthrax (6 papers, 2007 to 2022). "In the case of Bacillus anthracis infection, murine models suggest that protection against anthrax generated by an inactivated spore vaccine is dependent on IFNγ release by Th1 cells." (PMID 26075052, 2015). "The primary importance of humoral immunity in mediating protection against anthrax has been brought into question by recent studies suggesting that IFNγ producing CD4+ T cells play an important role in long lasting immunity." (PMID 24788397, 2014). "Our own recent research has shown that LF specific IFNγ producing CD4+ T cells play an important role in generating long lasting immunity to anthrax." (PMID 23162703, 2012). "Heat map representation of the epitope mapping results were observed for positive CD4+ T cell IFNγ ELIspot responses in the human donor cohorts, comprising a total of 9 donors in the cutaneous anthrax (Kayseri) group and 10 donors in the AVP vaccinees (UK) group." (PMID 36298436, 2022). "Thus, cutaneous anthrax induces a broad T cell memory response characterized not only by the presence of Th1 cytokines IFNγ and TNFα, but also Th2 (IL-5 and IL-13), Th17 (IL-17/IL-22), Th22 (IL-22) and Th9 (IL-9) cytokines and a potentially regulatory IL-10 response." (PMID 26075052, 2015).
Ascites (6 papers, 2017 to 2023). Accumulation of fluid in the peritoneal cavity (between the layers of the peritoneum that lines the abdomen). "The observed IFNγ-mediated restoration of the inducibility of IL-12 in the presence of ascites provides a possible explanation for the association of an interferon signaling-associated signature with a favorable clinical outcome." (PMID 28327095, 2017). "High levels of IL-12p40 can be produced by MDMs, and this is suppressed by ascites but overcome in the presence of IFNγ." (PMID 29997615, 2018). "Indeed, it was shown that IFNγ is capable of relieving suppression of IL-12 production by OC ascites and is, therefore, required for the pro-inflammatory feedback loop." (PMID 29997615, 2018). "Furthermore, previous studies showed deregulation of different mediators, illustrated by the upregulation of pro-inflammatory cytokines such as IL1β, IL6, TNFα, MIP1α, RANTES, and IFNγ in peritoneal effusions and serum samples of FIP clinical cases." (PMID 28388950, 2017). "However, in general, MX1, viperin, CXCL10, CCL8, RANTES, KC, MCP1, IL8, GM-CSF and IFNγ were readily detected in FCoV-positive cats whereby MX1 and viperin expression was higher in FCoV-positive cats with peritoneal effusions." (PMID 28388950, 2017).
Atrophy (6 papers, 2015 to 2023). Any weakening or degeneration, especially through lack of use. "Infection by M. avium strain 25291 results in severe thymic atrophy, a process dependent on the synergy between GC and NO produced by IFNγ activated Mφ." (PMID 34987496, 2021). "Together our data suggests that M. avium-induced thymic atrophy results from a combination of defects mediated by IFNγ and NO, including alterations in the BM T cell precursors, the thymic structure and the thymocyte differentiation." (PMID 34987496, 2021).
autoinflammatory syndrome (6 papers, 2016 to 2023). A group of disorders of the innate immune system characterized by attacks of seemingly unprovoked inflammation without significant levels of either autoantibodies or autoreactive T cells more characteristic of autoimmune disease. "Yeti mice on the C57BL/6 (B6) genetic background (hereafter Yeti mice) display autoinflammatory syndromes due to abnormal IFNγ expression." (PMID 36499642, 2022). "Yeti mice on the C57BL/6 (B6) genetic background (hereafter referred to as Yeti mice) display autoinflammatory syndromes due to abnormal IFNγ secretion." (PMID 33513946, 2021). "However, some studies raise concerns about IFNγ or TNF systematic upregulation promoting tissue damage or other autoinflammatory syndromes in patients." (PMID 37752135, 2023). "However, these Yeti mice have recently been reported to display autoinflammatory syndromes mediated by chronically elevated levels of IFNγ due to enhanced stability of IFNγ mRNA transcripts by using a polyA bovine growth hormone sequence." (PMID 30333822, 2018).